WDR4 (WDR4 tRNA N7-guanosine methyltransferase non-catalytic subunit)
Diseases named in the same sentence as WDR4 in open-access papers (continued):
Sharing a sentence is not in itself a finding about the gene and the disease.
tumor (52 papers, 2019 to 2026). "Together, these results confirmed that the m7G tRNA methyltransferases METTL1 and WDR4 are pathologically and clinically associated with tumor aggressiveness and poor survival outcomes in patients with PTC." (PMID 40360483, 2025). "In HCC patient tissues, METTL1 and WDR4 expression levels are positively correlated, and their high expression is associated with advanced tumor stage and poor prognosis, suggesting a synergistic oncogenic role." (PMID 41562049, 2025). "In HCC, upregulation of METTL1 and WDR4 is associated with advanced tumor stage, vascular invasion status, and poor patient survival." (PMID 39850560, 2024). "In HCC, the overexpression of METTL1/WDR4 is associated with advanced‐stage tumours and a poor prognosis." (PMID 38943267, 2024). "Upregulation of METTL1 and WDR4 was associated with advanced tumor stage, vascular invasion status, and poor patient survival." (PMID 39850560, 2024). "Our TMB and MSI analyses for METTL1 and WDR4 reflected the mutation frequency and proportion at the molecular level in different tumors and showed the correlation between mutation load and tumor progression." (PMID 36226166, 2022). "Our team studied the expressing level of 2 m7G-associated genes METTL1 and WDR4 in 18 tumor types and found that these two m7G-related genes were differentially expressed in many tumors, showing significant heterogeneity." (PMID 35812727, 2022). "The expression level of WDR4 is also strongly associated with tumor immunity, such as immune scores and tumor-infiltrating immune cells." (PMID 36226166, 2022). "The results of this study provide information regarding the role of WDR4 in tumours, reveal the relationship between WDR4 and tumour-immune interactions, and clarify the potential underlying mechanisms." (PMID 34282052, 2021). "The expression level of WDR4 is also strongly associated with tumour immunity, such as immune scores and tumour-infiltrating immune cells." (PMID 34282052, 2021). "The level of WDR4 is related to microsatellite instability and tumour mutation burden in several types of malignancy, and validation studies implied that WDR4-associated terms and pathways are involved in malignancy." (PMID 34282052, 2021). "In HCC and ICC, knockout of METTL1/WDR4 lowers global tRNA m7G levels, suppresses codon‐biased translation of cell‐cycle and survival mRNAs, and attenuates tumour growth in vitro and vivo." (PMID 41208200, 2025). "Mechanistically, the tumor-promoting WDR4 acts as an E3 ligase substrate adaptor to trigger PTPN23 proteasomal degradation, which diverts the fate of MVBs towards exosome secretion." (PMID 40908470, 2025). "This modification exerts selective control over the selective translation of oncogenic mRNAs governed by a codon frequency–dependent mechanism, primarily orchestrated by the METTL1/WDR4 complex, thereby influencing tumour growth and malignancy." (PMID 41208200, 2025). "Mechanistically, the context determinants that toggle METTL1/WDR4 outputs between oncogenic, codon‐biased selective translation and miRNA‐centred tumour suppression are incompletely resolved at the patient level." (PMID 41208200, 2025). "Among them, m7G acts through METTL1/WDR4 and eIF4E to shape translation and RNA processing across coding and non‐coding transcripts, yielding oncogenic or tumour‐suppressive outputs in a context‐dependent manner." (PMID 41208200, 2025). "The expression of METTL1 and WDR4 in PTC tumor tissues was significantly greater than that in normal tissues." (PMID 40360483, 2025). "The METTL1 / WDR4 complex currently promotes tumor development by mediating tRNA m7G methylation modification." (PMID 37528384, 2023). "A new regulatory mechanism was revealed in which WDR4 acts as an adaptor to promote transcriptional inhibition of tumor suppressor genes." (PMID 37783676, 2023). "WDR4 was upregulated in tumor tissues compared to normal adjacent tissues, and there was a correlation between the intensity of WDR4 staining and T stage." (PMID 37783676, 2023).
tumor (continued). "In this study, a co-expression network of METTL1 / WDR4 was constructed by Pearson correlation coefficient based on TCGA-HCC cohort (tumor: n = 370) using R software "WGCNA "package." (PMID 37528384, 2023). "This indicates that the immunoregulatory effect of METTL1 is greater than that of WDR4 in the tumor microenvironment." (PMID 36635678, 2023). "Knockdown of WDR4 significantly decreased tumor volume and weight, while overexpression of WDR4 markedly increased the volumes and weights of the tumors." (PMID 37783676, 2023). "We found a positive and significant correlation between METTL1 and WDR4 expression and PI3K enhanced pathway activation, indicating that METTL1 and WDR4 expression is increased in advanced PCa tumours." (PMID 37516825, 2023). "Previous studies have shown that WDR4 regulates the translation or degradation of tumor-related proteins in the cytoplasm after binding to interacting proteins." (PMID 37783676, 2023). "To evaluate the clinical relevance of METTL1 and WDR4 in patients with BC, we performed IHC analysis of the METTL1 and WDR4 proteins with TMAs, quantifying the positive staining of tumor cells." (PMID 37868988, 2023). "High mutation rates of METTL1 and WDR4 showed significant correlations in certain tumors, and the combination of the two biomarkers could be used to construct a precise model for predicting tumor progression and response to immunotherapy in BRCA, STAD, and LGG." (PMID 36226166, 2022). "Depletion of WDR4 led to significantly slower tumor growth, reduced tumor sizes and weights in vivo." (PMID 35304469, 2022). "In our study, high expression of WDR4, EIF4G1 and SLBP were significantly associated with a poor OS (p < 0.001) and increased tumor stem cell score in LUAD." (PMID 36226166, 2022). "The high expression of METTL1 and WDR4 is not only related to advanced tumor stage and grade but also to poor clinical outcome in patients with HCC." (PMID 35590385, 2022). "For example, METTL1 and WDR4 serve as tumor promoters, resulting in tumor growth, invasion and metastasis in hepatocarcinoma, esophageal squamous cell carcinoma, glioma, head and neck squamous cell carcinoma and non-small cell lung cancer." (PMID 36358764, 2022). "METTL1 and WDR4 carry out tumor-promoting functions, enhancing the growth, migration, and invasion of ICC cells." (PMID 35590385, 2022). "A previous study reported that WDR4 promotes the proteasomal degradation of promyelocytic leukemia (PML) tumor suppressor in LC." (PMID 35590385, 2022). "The levels of METTL1 and WDR4 are elevated in HCC and associated with advanced tumour stages and poor patient survival." (PMID 34898034, 2021). "For most TCGA-derived malignancy types, we discovered significantly upregulated WDR4 expression between tumour samples and paired normal samples, except for in the TCGA-KICH and TCGA-PAAD cohorts." (PMID 34282052, 2021). "Taken together, WDR4 depletion reduces m7G tRNA modification and leads to less malignant tumour behaviour in HCC cells, further supporting the importance of m7G tRNA modification in HCC progression." (PMID 34898034, 2021). "In our study, we aimed to investigate the expression of WDR4 and its prognostic significance in human tumours using data from the TCGA." (PMID 34282052, 2021). "Our findings showed the efficacy of WDR4 inhibitors on tumour growth in HCC patients and showed the possibility of their combined use with sorafenib, paving the way to develop new treatment strategies and therapeutic drugs for HCC in the future." (PMID 34244479, 2021). "Clinical data showed that WDR4 is associated with tumour metastasis, and our results further showed that the transfer of WDR4 is primarily mediated by EMT and that high WDR4 expression can cause sorafenib resistance." (PMID 34244479, 2021). "Tumour growth in the sh-WDR4-2 group was significantly slower than that observed in the sh-NC group, and the tumour weight was significantly reduced." (PMID 34244479, 2021).
tumor (continued). "UALCAN database analysis demonstrated that WDR4 transcript levels were significantly correlated with tumour grade and stage." (PMID 34244479, 2021). "However, no obvious differences in the expression levels of METTL1 and WDR4 were observed with respect to tumor stage and lymph node metastasis." (PMID 38822363, 2024). "In addition, WDR4 activates the transcription of tumor promoting gene MYC, and promotes the binding of EIF2A and Cyclin B1 (CCNB1) mRNA to enhance the translation of CCNB1, thus promoting the development of HCC." (PMID 39850560, 2024). "In addition, the tumor survival dependence of WDR4, the METTL1 methyltransferase partner, is not only significantly correlated with that of METTL1, but also shows close relationship with these pathways." (PMID 39198433, 2024). "In addition to NUDT16 being a protective factor, the other three genes (WDR4, EIF4E2, and SNUPN) are risk factors that accelerate tumor progression." (PMID 38987843, 2024). "Of note, previous studies identified that Wdr4 exerts multiple functions, such as regulating tumor microenvironments, stabilizing tRNA, and maintaining genome stability, through interacting with different partners/effectors, including DDB1/PML, METTL1, and FEN1, individually." (PMID 36681682, 2023). "Recent studies have shown that the METTL1 / WDR4 complex can promote tumor progression." (PMID 37528384, 2023). "To confirm whether METTL1 and WDR4 expression could correlate with advanced tumour status, we measured PI3K pathway activity by phosphorylation status of S6K, which altered in in approximately 70% of patients with advanced PCa." (PMID 37516825, 2023). "Upregulation of the METTL1/WDR4 complex promotes tumor development and metastasis." (PMID 37710294, 2023). "Reduced modification and therefore reduced translation of tumor-related mRNAs result from the depletion of the m7G modification enzymes METTL1/WDR4, which affects the potential of tumor cell division, colony formation ability, tumor cell migration and invasion ability and tumorigenic potential." (PMID 38201505, 2023). "In human beings, methyltransferase-like 1 (METTL1) and the WD repeat domain 4 (WDR4) are the most well-studied regulators of m7G, and have been reported to participate in tumor progression by regulating tumor immunity, metabolic reprogramming, and drug resistance." (PMID 36428620, 2022). "It was shown that the suppression of METTL1 or WDR4 in tumor cell lines in in vitro experiments leads to the arrest of cell proliferation, increased apoptosis, reduced colony formation and migration, and reduced tumor formation in in vivo experiments." (PMID 36012529, 2022). "However, the combination of WDR4 knockdown and sorafenib treatment resulted in the most significant inhibition of tumour growth." (PMID 34244479, 2021). "Next, we attempted to further confirm the role of WDR4 in sorafenib resistance in vivo and observed that either WDR4 knockdown or sorafenib treatment could inhibit tumour growth." (PMID 34244479, 2021). "The RNA methyltransferase WDR4 plays a key role in translation and tumour progression." (PMID 34244479, 2021). "Additionally, the WDR4 mRNA and protein levels in tumours and adjacent normal tissues of 80 HCC patients were determined by qRT-PCR, Western blotting, and immunohistochemical (IHC) staining." (PMID 34244479, 2021). "Furthermore, we discovered that WDR4 levels can serve as a valuable prognostic biomarker for some types of tumour." (PMID 34282052, 2021). "The METTL1/WDR4 complex performs m7G modification at position 46 of the tRNA ring to enhance mRNA translation by weakening ribosome suspension, thereby regulating self-renewal and differentiation of embryonic stem cells and playing a role in promoting tumor progression." (PMID 39850560, 2024). "In addition, METTL1 and WDR4 drive drug resistance by altering the tumor microenvironment." (PMID 37710294, 2023).
tumor (continued). "Furthermore, the result showed that the m7G methyltransferase WDR4 is a tumour promoter in the development and progression of HCC and may act as a candidate therapeutic target in HCC treatment." (PMID 34244479, 2021). "To investigate the clinical significance of METTL1-mediated codon-specific translation of TNF-α in PTC patients, we utilized PTC tumor tissues to validate the translational and clinical relevance of METTL1, WDR4, and TNF-α interactions." (PMID 40360483, 2025). "In OSCC, METTL1/WDR4‐driven tRNA m7G modification enhances the selective translation of growth and EMT‐related transcripts, driving tumour progression." (PMID 41208200, 2025). "In oral squamous cell carcinoma (OSCC), evidence indicates that METTL1/WDR4‐driven tRNA m7G enhances selective translation of growth and EMT programmes, thereby promoting tumour progression." (PMID 41208200, 2025). "Upregulation of the METTL1/WDR4 complex in NPC induces epithelial–mesenchymal transition (EMT) by activating the Wnt/β-catenin signaling pathway, thereby enhancing tumor metastasis." (PMID 41446042, 2025). "In this review, we not only focus on the structure and mechanism of m7G modified writers METTL1 and WDR4, as well as reader QKI, but also on the role of m7G in the digestive system, including digestive system tumors and non-tumor diseases." (PMID 39850560, 2024). "We also revealed that the METTL1/WDR4 complex promoted cell proliferation, inhibited cell apoptosis in AML cells, suggesting that METTL1 acts as a tumor accelerator in AML." (PMID 38268051, 2024). "Studies have indicated that silencing METTL1/WDR4 suppresses HCC progression, while its expression promotes tumour proliferation, migration, and invasion." (PMID 38943267, 2024). "The effect of m7G on ICC is mainly reflected by the tumor promoting function of METTL1 and WDR4, mainly affecting cell cycle arrest and translation damage, with cell cycle arrest occurring after translation damage." (PMID 39850560, 2024). "Second, in terms of chemoresistance, WDR4 can increase the translation of TRIM28, thereby enhancing the stemness of tumor stem cells, promoting HCC resistance to Lenvatinib and tumor progression." (PMID 39850560, 2024). "WDR4 has two main effects on HCC, promoting the proliferation of tumor cells and their chemoresistance." (PMID 39850560, 2024). "First, in terms of promoting tumor cell proliferation, WDR4 induces G1/G0 cell cycle transformation, inhibits apoptosis, promotes proliferation of HCC cells, and significantly increases tumor size and weight." (PMID 39850560, 2024). "WDR4 forms a methyltransferase complex with Methyl transferase-like protein 1 (METTL1), promoting the translation of tumor-related mRNA by influencing m7G modification of tRNA." (PMID 37783676, 2023). "The methyltransferase complex formed by WDR4 and METTL1 promotes the translation of the target mRNAs and promotes tumor progression." (PMID 37783676, 2023). "Firstly, the expression of METTL1 and WDR4 is significantly increased at both the mRNA and protein levels in ICC as compared with that in peri-tumor tissues, and these also act as poor survival predictors in ICC patients." (PMID 35590385, 2022). "In tumor tissues, EIF4E and NCBP2 were highly expressed, while WDR4 and NCBP1 were moderately expressed." (PMID 35784919, 2022). "The inhibition of METTL1 and WDR4 weakens tumorigenesis of NPC, which significantly restrains the tumor growth, migratory, and invasion features, and increases cell apoptosis both in vivo and in vitro." (PMID 35590385, 2022). "Inhibition of METTL1 or WDR4 is an effective method to decrease ESCC progression both in vitro and in vivo, including impairing tumor proliferative capacity and tumor formation." (PMID 35590385, 2022). "More than half of the m7G-related genes were significantly upregulated in tumor samples, such as METTL1, WDR4, EIF4E, LARP1, and LSM1." (PMID 36761423, 2022).
tumor (continued). "WDR4 protein levels were significantly increased in HCC, while WDR4 mRNA levels were positively correlated with tumour size, TNM stage, BCLC stage, PVTT, and lymph node metastasis." (PMID 34244479, 2021). "Notably, a PTPN23-derived short peptide that blocks the interaction between WDR4 and PTPN23 enables PTPN23 stabilization to promote MVB degradation in tumor cells, thereby reducing exosome secretion." (PMID 40908470, 2025). "Orthotopic transplantation models showed that both METTL1 knockout and WDR4 knockdown significantly hindered tumour growth and lymph node metastasis." (PMID 41208200, 2025). "Notably, DCPS manifested pronounced expression in both neoplastic and non‐neoplastic tissues, while DCP2, NCBP2, WDR4, and NUDT3 demonstrated intermediate expression across tumor and normal samples." (PMID 40485623, 2025). "Furthermore, tissue microarray analysis confirmed a significant positive correlation among METTL1, its cofactor WDR4, and TNF-α expression levels in PTC tissues, highlighting their cooperative role in driving tumor aggressiveness." (PMID 41562049, 2025). "In addition, the expression level of METTL1 was positively correlated with that of WDR4 and TNF-α in PTC tumor tissues, and WDR4 expression was also positively correlated with TNF-α expression." (PMID 40360483, 2025). "Additionally, the m7G methyltransferase WD repeat domain 4 (WDR4) is abnormally upregulated and promotes tumor metastasis and sorafenib resistance through EMT." (PMID 39473440, 2024). "Notably, mRNA levels of LARP1, METTL1, WDR4, and NCBP1 were upregulated in tumor specimens." (PMID 40485623, 2025). "WDR4 expression in tumor cell nuclei has not been reported thus far." (PMID 37783676, 2023). "The function and mechanism of WDR4 in the nucleus of tumor cells has not been investigated." (PMID 37783676, 2023). "Inducible silencing of WDR4 did not reduce cell or tumour growth." (PMID 37516825, 2023). "In addition, METTL1/WDR4 had a better ability to distinguish tumor from non-tumor (AUC > 0.6) based on ROC curves." (PMID 37528384, 2023). "WDR4 can negatively regulate PML via ubiquitination to drive lung tumour development by fostering the development of an immune-suppressive and premetastatic tumour microenvironment, indicating the potential of immune-modulatory methods for treating lung carcinoma." (PMID 34282052, 2021). "We further observed a negative correlation between WDR4 expression and PTPN23 expression in tumor tissues." (PMID 37821451, 2023). "Based on the hormonal dependency of PCa tumours, expression analysis of METTL1, WDR4 and AR was performed, but no significative correlation was found between METTL1, WDR4 and AR expression." (PMID 37516825, 2023). "The protein expressions of METTL1, NSUN2, EIF4G3, LARP1, NCBP1, and NCBP2 were higher in tumor tissues than in normal tissues; however, the protein expressions of WDR4, EIF4E1B, and NCBP2L were negative in both tumor and normal tissues." (PMID 35785179, 2022). "In tumor biopsies from non-responders, GPR110 and TNIK were significantly upregulated, while WDR4 and BRCA1 were significantly downregulated, as compared to those of responders (p < 0.05)." (PMID 34572869, 2021).